RNF157-AS1 (RNF157 antisense RNA 1)
Gene: Long non-coding RNA gene on chromosome 17 (76,138,425 to 76,154,650, forward strand). Ensembl gene ENSG00000267128.
Diseases named in the same sentence as RNF157-AS1 in open-access papers:
RNF157-AS1 is named in the same sentence as 1 disease in open-access papers, as found by Europe PMC text mining. Sharing a sentence is not in itself a finding about the gene and the disease. The quoted sentences say what the papers report.
epithelial ovarian cancer (1 paper, 2023). "Analyses of several databases showed that the lncRNA RNF157 Antisense RNA 1 (RNF157-AS1) is overexpressed in epithelial ovarian cancer (EOC) tissues." (PMID 36805591, 2023).